SCGB2B2 (secretoglobin family 2B member 2)
Synonyms: SCGB4A2; SCGBL
Tractability: Antibody: UniProt places it where antibodies can reach, with high confidence; UniProt predicts a signal peptide or a membrane-spanning region; its Gene Ontology location is reachable by antibodies, with medium confidence.
Gene: Protein-coding gene on chromosome 19 (34,590,644 to 34,677,159, reverse strand). Ensembl gene ENSG00000205209.
Subcellular location: Secreted
Gene Ontology:
Molecular function: protein binding
Cellular component: extracellular region
Genetic constraint (gnomAD): Loss-of-function variants: 13 observed, 8.71 expected, observed/expected ratio (o/e) 1.49, 90% interval 0.94 to 1.93. That is too few expected variants to judge how well the gene tolerates losing a copy. Missense variants: 101 observed, 114.78 expected, observed/expected ratio (o/e) 0.88, 90% interval 0.75 to 1.04. Synonymous variants: 48 observed, 48.86 expected, observed/expected ratio (o/e) 0.98, 90% interval 0.78 to 1.25.
Homologues: Orthologues: chimpanzee SCGB2B2 (97% identical).
Diseases named in the same sentence as SCGB2B2 in open-access papers:
SCGB2B2 is named in the same sentence as 1 disease in open-access papers, as found by Europe PMC text mining. Sharing a sentence is not in itself a finding about the gene and the disease. The quoted sentences say what the papers report.
hypospadias (1 paper, 2015). Hypospadias is the displacement of the urethral meatus on the ventrum of the penis. "This hypothesis can be ruled out for SCGB2B2 since this gene is not expressed in skin cells and is not likely for WTIP gene because its haploinsuffiency has been pointed as a cause for hypospadias." (PMID 25883683, 2015).